TSLP (thymic stromal lymphopoietin)
Diseases named in the same sentence as TSLP in open-access papers (continued):
Sharing a sentence is not in itself a finding about the gene and the disease.
tumor (continued). "Therefore, the mechanisms by which TSLP exerts its dual effects vary among different tumor types." (PMID 40787610, 2025). "We documented up-regulation in the expression of IFN-γ, IL12p70, IL-18, IL-20, MIF, TNF-α, TSLP, BLC, Eotaxin-1, Eotaxin-2, IP-10, MIP-1a, MIP-3a, FGF-2, MMP-1, TNFRII and TWEAK, which are implicated in the modulation of inflammation, apoptosis, tumor growth, invasion, and angiogenesis." (PMID 38954024, 2024). "However, recent researches have also suggested that TSLP might have both pro-tumorigenic and antitumor effects, and its activity depends on the tumor microenvironment context and the cancer type." (PMID 37809098, 2023). "To investigate whether the tumor-promoting effect of TSLP involves signaling through TSLPR expressed by DCs, we generated mice with the ablation of TSLPR selectively in DCs by breeding mice bearing the floxed allele of the Crlf2 gene with CD11c-Cre transgenic mice." (PMID 36107619, 2022). "Thus the increase in plasma TSLP levels could be linked to chemo-resistance due to the more aggressive tumor cell behavior, given that the unresponsive patients under GEMOX treatment showed slightly increased circulating levels of TSLP." (PMID 30214685, 2018). "Furthermore, TSLP immunostaining showed that the epithelium of normal mucosa in tumor-surrounding tissues was positively stained with TSLP, which is consistent with the previous findings that colon epithelial cells constitutively express TSLP." (PMID 26919238, 2016). "Thus, the discrepancy could be explained by the different type of target cell of TSLP and the relative contribution of TSLP-regulated immune response to the growth of different tumor types." (PMID 26919238, 2016). "In vivo experiments showed the presence of Th2-attracting chemokines in the tumor and stroma, and the intratumoral infiltration of Th2 cells was found to correlate with CAF-derived TSLP production and reduced patient survival." (PMID 40453074, 2025). "Our group previously demonstrated the presence of TSLP in GBM tumor cells and its possible role as a modulator of neutrophil physiology in the tumor microenvironment." (PMID 41516199, 2025). "However, future additional experimental validation of CSF2 and its regulation, as well as proper exclusion of IL-13 and TSLP in the effects of NCTD on CRC or other types of tumor cells may provide further insights into the particular anticancer mechanism of NCTD." (PMID 40394236, 2025). "Despite of this, based on the transcriptional profiles, ILC2 is a heterogeneous population wired with functional plasticity promoted by growing tumour environment, and this plasticity can be further inflated by IL33/TSLP stimulation." (PMID 38172434, 2024). "In this work, we show that GBM cells produce TSLP when stimulated with EGF, a crucial growth factor prevalent in this tumor microenvironment." (PMID 38557942, 2024). "Despite of the stable maintenance of type 2 identity observed in the majority of the total ILC2s across different conditions, other clusters seem to have immunological plasticity that responds to the presence of tumour growth and IL33/TSLP stimulation." (PMID 38172434, 2024). "IL‐25, IL‐33 and thymic stromal lymphopoietin (TSLP) activate ILC2s and induce ILC2s to secrete type 2 cytokines such as IL‐5 and IL‐13 to mediate tumor killing." (PMID 39401416, 2024). "In conclusion, our results position TSLP as a possible new growth factor in GBM and indicate its modulation of the tumor microenvironment, particularly through its interaction with PMN." (PMID 38557942, 2024). "It has been shown that high-dose of thymic stromal lymphopoietin (TSLP) can induce apoptosis, impeding the proliferation and migration of CRLF2 B-ALL tumor cells." (PMID 38566223, 2024). "Detection of a negative correlation (i.e., Rho: -0.317, p < 0.00015) between non-Tumor and GMB cells of TSLP expression level indicates that TSLP is predominantly expressed in the microenvironment cells (e.g., neutrophils)." (PMID 38557942, 2024).
tumor (continued). "Arctigenin, a bioactive compound from Arctium lappa L., also binds to ERs and reduces pro-tumor signals, such as granulocyte-macrophage colony-stimulating factor (GM-CSF), MMP-3, MMP-9, and thymic stromal lymphopoietin (TSLP)." (PMID 37895937, 2023). "Expression analysis through qPCR showed that IL‐37tg expressed a lower level of the stem cell marker TSLP and IFN‐γ in tumor‐bearing skin tissues and SDLN as compared with WT mice." (PMID 36891351, 2023). "With the participation of TSLP as an enhancer, TSLP-activated DCs can induce much robust CD8+ T cell expansion, thus providing more efficient anti-tumor immunotherapies than historically used adjuvant Bacillus Calmette–Guérin." (PMID 37809098, 2023). "Eosinophil mediators, such as IL-5, IL-33, granulocyte–macrophage colony-stimulating factor (GM-CSF), thymic stromal lymphopoietin (TSLP), and CCL11 also determine eosinophil behavior toward tumor cells." (PMID 37587450, 2023). "Antibodies neutralizing TSLP or OX40L inhibited IL-13 production and tumor growth in a xenograft model." (PMID 37835465, 2023). "A total of 30 IL22RA1-correlated genes (e.g. IL17D, IL22RA2, IL20RB, IL10RA, IL10RB, TSLP and TYK2) are involved in the JAK/STAT pathway which promotes tumor progression." (PMID 35874683, 2022). "Importantly, the significantly higher lymphoid aggregate counts in Tslptg KrasG12D compared with Tslptg mice suggests that TSLP-activated T cells in the lungs are responding to the tumor antigens as opposed to a nonspecific allergic inflammation caused by TSLP overexpression alone." (PMID 35565302, 2022). "CD4+ T cells were sorted from tumors and tumor-draining lymph nodes of Tslp transgenic (test) or Tslpr knockout (TslprKO, control) mice and stimulated ex vivo using anti-CD3/CD28 antibodies plus TSLP." (PMID 36467403, 2022). "TSLP, along with TSLPR, plays a dual role in tumor progression, either inducing or preventing the tumor formation depending on the tumor type." (PMID 34573368, 2021). "For this reason, we evaluated the relation of TSLP, TSLPR, and IL-7R SNPs with CRC development based on the tumor location." (PMID 34573368, 2021). "Thymic stromal lymphopoietin (TSLP) is an immunosuppressive IL-17-like cytokine that promotes Th2-dominant immune responses and facilitates tumor progression." (PMID 32595757, 2020). "Pedroza-Gonzalez showed that inflammatory Th2 cells that promoted tumor development were driven by cancer cell-derived TSLP, which induced and maintained OX40L-expressing DCs in the tumor microenvironment." (PMID 32351590, 2020). "We present a new method for profiling the metabolic rate in OAC tumour biopsies in real-time and demonstrate the significant correlation OCR with the secreted levels of VEGF-A, IL-1RA and TSLP." (PMID 32694701, 2020). "Our finding indicated that arctigenin decreased the expression of tumor-derived cytokines, including GM-CSF, MMP-3, MMP-9 and TSLP." (PMID 32887217, 2020). "Our data also showed that YPF decreased the levels of TSLP, TSLPR, and OX40L, increased the expression of CD80, CD86, and MHC-II in DCs, and stimulated the maturation of DCs in tumor and adjacent tissues of mice bearing with HCC." (PMID 32351590, 2020). "In this study, YPF increased the percentage of mature dendritic cells (DCs) and decreased levels of TSLP, TSLPR, and OX40L in tumor and adjacent tissues of the orthotopic-HCC mice model." (PMID 32351590, 2020). "Tumor cells under hypoxia expressed TSLP, and TSLPR was expressed in both tumor cells and vascular endothelial cells." (PMID 33042121, 2020). "OCR was positively correlated with three secreted factors in the tumour conditioned media: vascular endothelial factor A (VEGF-A), IL-1RA and thymic stromal lymphopoietin (TSLP)." (PMID 32694701, 2020). "Compared with the model control group, YPF decreased the levels of TSLP, TSLPR, and OX40L in tumor and adjacent tissues (p < 0.05, p < 0.01)." (PMID 32351590, 2020).
tumor (continued). "TSLP signaling can induce VEGF activation through the JAK/STAT pathway and thereupon promote angiogenesis in the tumor microenvironment." (PMID 32595757, 2020). "OCR positively correlated with three secreted factors in OAC tumour conditioned media: VEGF-A, IL-1RA and TSLP." (PMID 32694701, 2020). "In our study that YPFS inhibit the angiogenesis by decreasing the expression of TSLP/STAT3, which is in accordance with the improvement of immunosuppression of the tumor microenvironment." (PMID 31885639, 2019). "Studies have reported that TSLP and TSLPR expression in the tumor cells contributes to tumor growth following tumor microenvironment Th2 cell differentiation." (PMID 31885639, 2019). "Thymic stromal lymphopoietin (TSLP) has emerged as an important, but contradictory, player conditioning tumor growth." (PMID 30214685, 2018). "Thymic stromal lymphopoietin (TSLP) has recently been suggested in several epithelial cancers, either pro-tumor or anti-tumor." (PMID 26919238, 2016). "The effects were systemic, as levels of thymic stromal lymphopoietin (TSLP), tumour-necrosis factor (TNF)-α and interleukin (IL)-6 were elevated in serum of tumour-free InvEE mice and increased further in tumour-bearing animals." (PMID 25575023, 2015). "Importantly, skin-derived TSLP, which can be induced by an FDA-approved topical medication, calcipotriol, can reach and activate CD4+ T cell–mediated antitumor immunity in the tumor microenvironment (TME)." (PMID 39782693, 2025). "In this work, we also demonstrate that TSLP increased CHRM3 expression in the U251 cell line, enhancing tumor malignancy, probably by further promoting the complex interaction of GBM cells with the brain microenvironment and their tendency to aggressively infiltrate normal brain tissue." (PMID 41516199, 2025). "The mechanisms by which high-dose TSLP induces tumor cell apoptosis have not been comprehensively studied." (PMID 40787610, 2025). "Collectively, we found that ANK-SNs did not have cytotoxic effects, were efficiently internalized through specific interaction at the cell surface with IL-1R1, and down-modulated the secretion by CAFs of TSLP, IL-8, IL-6, and TGF-β, thus dampening their tumor-promoting functions." (PMID 39125655, 2024). "In our model, TSLP production is induced only when cells are stimulated with EGF, suggesting a potential loop mechanism or positive feedback between the effects of EGF on the tumor and TSLP production." (PMID 38557942, 2024). "The authors demonstrated that TSLP signals through TSLPR are expressed by dendritic cells and promote GATA3+ Th2 cells and GATA3+ Tregs with enhanced immunosuppressive functions on CD8+ T cells in tumor-draining lymph nodes and tumor sites." (PMID 39201498, 2024). "Prior to conducting the assay, we identified a subset panel of factors known to mediate the induction of apoptosis in tumor cells: IL-27, IL-1b, IL-2, CXCL10, IL-12p70, G-CSF, IFN-g, TNF-a, IFN-a, CCL2, IL-9, TNF-b, TRAIL, IL-18, IL-21, TSLP." (PMID 37468934, 2023). "Furthermore, under stimulation by tumor-derived TNF and IL-1, CAFs can produce thymic stromal lymphopoietin (TSLP), which promotes Th2 cell polarization through myeloid DC training." (PMID 37723510, 2023). "The fact that TSLP+ signals were detected in epidermal keratinocytes overlying tumors, but not healthy epidermal borders, suggests that tumor cells send signals that promoted epidermal TSLP production." (PMID 36107619, 2022). "CD4+ T cells were sorted from tumors and tumor-draining lymph nodes of Tslp-PyMttg (test) or MMTV-PyMTtg, Tslpr(Crlf2)−/− (PyMttg TslprKO; control) mice and stimulated ex vivo using anti-CD3/CD28 antibodies plus TSLP over one to three cycles." (PMID 35657353, 2022). "Additionally, in response to TSLP, tumor cells have been shown to be secreting IL-1α that act on myeloid cells in the TME, which subsequently secrete TSLP back to tumor cells, creating an IL-1α/TSLP positive feedback loop." (PMID 36467403, 2022).
tumor (continued). "Note that the comparison of RNA levels of these genes in the dorsal skin from WT and Tslp–/– mice did not reveal any difference, suggesting that their expression in tumor-free skin was not impacted by the absence of TSLP." (PMID 36107619, 2022). "In turn, these infiltrating macrophages establish a continuous crosstalk with tumor cells producing tumor-surviving factors such as epithelial growth factor (EGF), thymic stromal lymphopoietin (TSLP), and transforming growth factor beta (TGF-β) that leads to cancer cell proliferation." (PMID 34572013, 2021). "Consequently, the decrease of GM-CSF/TSLP muted STAT3/β-catenin signaling and inhibited tumor progression." (PMID 32887217, 2020). "It was suggested that YPF could decrease the levels of TSLP, TSLPR, and OX40L of tumor microenvironment in mice bearing with HCC." (PMID 32351590, 2020). "Overexpression of GM-CSF and TSLP made arctigenin failed to elongate the survival of tumor-bearing mice, failed to reduce tumor volume and weight." (PMID 32887217, 2020). "Therefore, we further observed the expression of TSLP, TSLPR, and OX40L in tumor and adjacent tissue after administration of YPF." (PMID 32351590, 2020). "In the majority of models Th2-independent mechanisms of TSLP in cancer rely on direct TSLP-TSLPR signaling in TSLPR-expressing tumor cells involving apoptotic pathways, tumor cell proliferation, signal transduction, and activation of remodeling and proangiogenic gene signatures." (PMID 33042121, 2020). "We found that TSLP secretion was significantly reduced when CAFs were activated with the supernatants of THP1 after treatment with the supernatant of ASC-silenced tumor cells, suggesting that indeed ASC expression and release by tumor cells indirectly contributed to TSLP secretion by CAFs." (PMID 30760333, 2019). "To probe into whether YPFS inhibited the tumor angiogenesis through affecting the activation of TSLP, we used the anti-TSLP antibody to detect the level of MVD and VEGF in tumor tissues." (PMID 31885639, 2019). "Our results showed that TSLP was overexpressed in EOC and suggested that it might be involved in tumor biology or development of EOC." (PMID 31023965, 2019). "d Tumor cell- and TAM-derived IL-1α and IL-1β, respectively, induce TSLP secretion by CAFs." (PMID 30760333, 2019). "To determine whether the expression of TSLP induced by YPFS was responsible for the inhibition of angiogenesis, we detected the expression of TSLP and TSLPR by ELISA in tumor tissue of HCC-bearing mice treated with YPFS." (PMID 31885639, 2019). "While some studies have provided evidence for a tumor-promoting role, other studies have shown that TSLP does not play any significant role in tumor progression." (PMID 29222519, 2017). "Significantly decreased TSLP mRNA expression and an approximate two-fold decrease in the average protein levels of TSLP (47.54±7.66 vs 22.46±5.09, n=40, p<0.01, mean±SEM) were detected in tumor tissues compared with tumor-surrounding tissues." (PMID 26919238, 2016). "Furthermore, TSLP-activated DCs (CD11c+ TSLPR+) were identified in the tumor stroma and draining lymph nodes, but not in non-draining nodes." (PMID 40453074, 2025). "In conclusion, our work proposes a new role for TSLP in GBM tumors, a cytokine present in the tumor microenvironment that may be acting directly on the tumor or through the modulation of the neutrophil physiology within the tumor microenvironment." (PMID 38557942, 2024). "Consequently, our results, exhibiting a negative correlation, indicate that TSLP is expressed mainly in the tumor microenvironment." (PMID 38557942, 2024). "TSLP has multiple functions in both homeostasis and pathological conditions, and this cytokine can act on B cells, DCs, CD4+ and CD8+ T cells, neutrophils, mast cells, basophils, eosinophils, type 2 innate lymphoid cells, natural killer T cells, smooth muscle cells and even tumour cells." (PMID 37165746, 2023).
tumor (continued). "Moreover, TSLP expression was increased after floating culture of the epidermis from WT mice on the medium of plated B16F10 cells, supporting the idea that epidermal TSLP expression was induced directly by signals derived from tumor cells." (PMID 36107619, 2022). "A tumor-myeloid cell axis independent of T cell response may mediate this tumor-promoting function of TSLP." (PMID 35432341, 2022). "In addition, Vetter and collaborators showed that in a fraction (about 20%) of patients with B cell precursor-acute lymphoblastic leukemia tumor cells expressed the TSLPR, and in vitro stimulation of leukemic cells with TSLP enhanced their proliferation and induced activation of STAT-5 signaling." (PMID 33042121, 2020). "In the light of the results of the in situ study performed by IHC on early stage PDAC tissue samples (in prevalence I/II stages), it is tempting to speculate that TSLP release occurs early in PDAC tumorigenesis and, once established, remains constant during the late phase of tumor progression." (PMID 30214685, 2018). "In addition, we have investigated the expression of IL-31, TSLP and their receptors in invaded lymph nodes from HL patients in view of the tumor promoting role of these cytokines and the complete lack of information on this latter issue." (PMID 29156718, 2017). "Importantly, TSLP treatment failed to inhibit TSLPRkd-SW1116-derived tumor growth, which was accompanied by similar tumor necrotic areas and apoptotic responses to those in control group without TSLP treatment." (PMID 26919238, 2016). "Development of TH2 cells, involved in responses against parasites (but detrimental in the setting of anti-tumor responses), is though to be induced by the lack of IL-12 as well as by IL-4, thymic stromal lymphopoietin (TSLP), and Matrix metalloproteinase 2 (MMP-2)." (PMID 24339825, 2013). "TSLP, a cytokine structurally related to IL-7, is produced by a variety of cell types and influences a diverse range of target cells, including immune cells like B cells, T cells, DCs, eosinophils, and NK cells, as well as non-immune cells such as smooth muscle and tumor cells." (PMID 40724851, 2025). "As not all tumor cells constitutively express/release IL-1, we hypothesized that tumor infiltrating myeloid cells, which are highly represented within the tumor microenvironment, could be an alternative source of IL-1 for induction of TSLP secretion by CAFs." (PMID 30760333, 2019). "To investigate the role of CD4+ T cells in TSLP-mediated tumor protection, we transferred naïve CD4+ T cells from WT mice into Rag1–/– (Rag1KO) mice with or without TSLP overexpression." (PMID 39744942, 2025).